LBP (lipopolysaccharide binding protein)
Diseases named in the same sentence as LBP in open-access papers (continued):
Sharing a sentence is not in itself a finding about the gene and the disease.
epilepsy (1 paper, 2026). A brain disorder characterized by episodes of abnormally increased neuronal discharge resulting in transient episodes of sensory or motor neurological dysfunction, or psychic dysfunction. "Correspondingly, serum LBP levels, indicative of barrier disruption and systemic inflammation, were significantly lower in the L. eligens-treated epilepsy group." (PMID 41356796, 2026).
esophageal cancer (1 paper, 2025). A primary or metastatic malignant neoplasm involving the esophagus. "Among these, the combination of TAX and LBP exhibited the highest inhibition rate, which was consistent with the findings of TAX combination therapy in esophageal cancer." (PMID 40740875, 2025).
extrahepatic cholestasis (1 paper, 2008). Impairment of the bile flow caused by an obstruction in the portion of the bile duct system located outside of the liver. "Kupffer cells are clearly altered in biliary obstruction, with an increased phagocytic ability and a marked proinflammatory response to endotoxin and the lipopolysaccharide binding protein (LBP), which are both increased in extrahepatic cholestasis." (PMID 19014418, 2008).
Fulminant hepatic failure (1 paper, 2020). Hepatic failure refers to the inability of the liver to perform its normal synthetic and metabolic functions, which can result in coagulopathy and alteration in the mental status of a previously healthy individual. "In vivo transdifferentiation of hBMSCs in pigs with fulminant hepatic failure confirmed the similarly upregulated expression of 5 hepatogenic genes (TDO2, HP, SERPINA3, LBP and SAA1), showing a 150-fold change in liver tissues at 7 days after hBMSC transplantation." (PMID 32038110, 2020). "Finally, the five genes (TDO2, HP, SERPINA3, LBP and SAA1) validated in hBMSC transplantation with a fulminant hepatic failure (FHF) model in pigs could be potential biomarkers for the characterization of hBMSC-HLCs." (PMID 32038110, 2020).
gastritis (1 paper, 2025). Inflammation of the stomach. "A different model, designed to predict cancer or preneoplasia vs. healthy or gastritis, yielded an even higher mAUROC of 83.9% (73.9–93.9% (95% CI)) and was based on the plasma concentrations of ARG1, HPT, CA2, MAN2A1, and LBP." (PMID 41155404, 2025).
gastroesophageal reflux (1 paper, 2023). "rs1363119 which was associated with increasing LBP levels has previously been associated with gastroesophageal reflux in European populations." (PMID 37756315, 2023).
hookworm infections (1 paper, 2012). "In contrast, in those who failed to cure their hookworm infection there were no significant alterations in the levels of LPS, LBP or sCD14 between those found pre- and 3 months following albendazole therapy." (PMID 23056659, 2012). "Although increased levels of LBP are a common feature of MT in other infections, we did not observe any significant alteration in LBP levels in hookworm infections." (PMID 23056659, 2012).
Hyperbilirubinemia (1 paper, 2019). An increased amount of bilirubin in the blood. "In our study, hepatic LBP expression was significantly higher in Gunn rats before and after LPS treatment, suggesting a role of hyperbilirubinemia in LBP-mediated LPS signaling." (PMID 31075981, 2019).
hyperhomocysteinemia (1 paper, 2020). A serious metabolic condition caused by mutations in the MTHFR gene, medications, or nutritional deficiency. "A pathway analysis model showed that hyperhomocysteinemia and HDD90 along with LBP and IL1β showed a significant cumulative effect on alcohol withdrawal in Gr." (PMID 33374263, 2020).
Hypoalbuminemia (1 paper, 2020). The concentration of albumin in the blood circulation is below the lower limit of normal. "Cirrhotic mice had the typical abnormalities of leucopenia, lymphopenia, thrombocytopenia, hypoalbuminemia, abnormal liver function, high serum C-reactive protein (CRP), and high lipopolysaccharide binding protein (LBP) levels." (PMID 32138352, 2020).
hypogonadism (1 paper, 2025). A disorder characterized by decreased function of the gonads. "In line with this, obese men with hypogonadism have shown elevated levels of lipopolysaccharide-binding protein (LBP) and pro-inflammatory cytokines, which negatively correlate with serum testosterone levels." (PMID 40906193, 2025).
Hypomagnesemia (1 paper, 2022). An abnormally decreased magnesium concentration in the blood. "This group exhibited inflammatory activity (LBP and TNFα) contributing to clinically significant hypomagnesemia." (PMID 36232646, 2022).
IgA nephropathy (1 paper, 2024). "Serum LBP level was also significantly increased in patients with IgA nephropathy, a separate disease that shares pathogenesis with IgAV." (PMID 38610060, 2024).
immunodeficiencies (1 paper, 2024). "ME/CFS patients without immunodeficiencies exhibit a mucosal barrier leakage, as indicated by elevated levels of Lipopolysaccharide-binding protein (LBP)." (PMID 38202282, 2024). "Elevated levels of the barrier marker LBP indicate mucosal barrier leakage in the ME/CFS patient group without immunodeficiencies." (PMID 38202282, 2024). "ME/CFS patients without immunodeficiency exhibited mucosal barrier leakage, indicated by elevated levels of the marker LBP, potentially contributing to low-grade inflammation." (PMID 38202282, 2024). "Altogether, we hypothesize that ME/CFS patients without immunodeficiencies suffer rather from epithelial leakage, as indicated by the elevated LBP level and the LBP/sCD14 ratio, and ultimately fail to maintain mucosal barrier function." (PMID 38202282, 2024). "However, following immunological patient stratification, serum LBP levels were found to be significantly increased in patients without immunodeficiencies (ME/CFS − ID) when compared to the healthy control group." (PMID 38202282, 2024). "However, when comparing the LBP/sCD14 ratio, we were again able to only detect a significantly higher ratio in ME/CFS patients without immunodeficiencies compared to the other test groups." (PMID 38202282, 2024).
insomnia (1 paper, 2024). A sleep disorder characterized by difficulty in falling asleep and/or remaining asleep. "Insomnia was not significantly correlated with IgA or IgG levels to bacterial, TJ, BBB, CATACT, and LPS + LBP composites, even without FDR p correction." (PMID 38379706, 2024).
intestinal inflammation (1 paper, 2024). "Fecal myeloperoxidase (MPO) and neopterin (NEO) were markers of intestinal inflammation whereas plasma lipopolysaccharide-binding protein (LBP) and C-reactive protein (CRP) were assessed as markers of systemic inflammation." (PMID 39775265, 2024).
intrahepatic cholestasis (1 paper, 2022). A cholestasis characterized by impairment of the bile flow caused by obstruction located in the liver. "The serum levels of lipopolysaccharide and lipopolysaccharide binding protein in women with intrahepatic cholestasis of pregnancy were analyzed." (PMID 36482374, 2022). "Our data indicated significantly elevated levels of lipopolysaccharide and lipopolysaccharide binding protein in women with intrahepatic cholestasis of pregnancy." (PMID 36482374, 2022).
Knee Osteoarthritis (1 paper, 2022). "Research has shown that, LPS and lipopolysaccharide-binding protein (LBP) were significantly associated with activated macrophages and osteophyte severity in the joints of Knee Osteoarthritis (KOA) patients." (PMID 36172610, 2022).
lipodystrophy (1 paper, 2021). A congenital or acquired disorder characterized by abnormal loss or redistribution of the adipose tissue in the body. "Age had the strongest positive association with lipodystrophy and also positively correlated with several inflammatory markers, including LBP, CRP, IL-6, ICAM-1, and serum amyloid A (SAA)." (PMID 34006628, 2021).
liver cancer (1 paper, 2025). An epithelial or non-epithelial malignant neoplasm that arises from the liver. "Lipopolysaccharide-binding protein concentrations were most strongly associated with higher liver cancer risk (OR per doubling in concentrations: 1.48, 95% CI: 1.23-1.79)." (PMID 41129365, 2025).
lung fibrosis (1 paper, 2022). "CD14 and LBP are mediators of lung inflammation that are produced in response to infectious processes and LRG1 is a hallmark of risk for lung fibrosis assessment." (PMID 35884998, 2022).
mastocytosis (1 paper, 2022). A clonal myeloproliferative neoplasm characterized by the proliferation and accumulation of neoplastic mast cells in one or multiple organs or organ systems. "Utilising this workflow, we identified and validated CXCL7, LBP, TGFβ1 and PDGF receptor-β as novel biomarkers for systemic mastocytosis." (PMID 35332176, 2022).
melanoma (1 paper, 2023). A malignant, usually aggressive tumor composed of atypical, neoplastic melanocytes. "The forest plot shows that IFNAR2, LBP, CXCL9, and TLR2 are the protective genes for melanoma, while RAC1 and MAPK10 are the risk genes for melanoma." (PMID 37666853, 2023). "By integrating a series of bioinformatics methods, our study identified 6 TLR-related genes (IFNAR2, RAC1, LBP, TLR2, MAPK10, CXCL9), which have the potential to serve as new indicators of melanoma progression and prognosis." (PMID 37666853, 2023). "Subsequently, employing a similar approach, we conducted a thorough analysis of the correlation between the clinical characteristics of melanoma and remaining five model genes, i.e. IFNAR2, LBP, MAPK10, RAC1, and TLR2." (PMID 37666853, 2023).
nosocomial infection (1 paper, 2026). An infection acquired in a hospital or other healthcare setting. "In multivariable analysis, LBP, CRP, and albumin remained independently associated with nosocomial infection." (PMID 41574679, 2026). "This study aimed to assess whether admission plasma lipopolysaccharide-binding protein (LBP), procalcitonin (PCT), and lactate could improve detection of nosocomial infection in cirrhotic patients presenting with upper gastrointestinal bleeding (UGIB)." (PMID 41574679, 2026). "Compared with noninfected patients, those with nosocomial infection had higher WBC, CRP, PCT, LBP, lactate, international normalized ratio (INR), and total bilirubin (TB), lower albumin and sodium, a higher neutrophil-to-lymphocyte ratio (NLR), and a lower lymphocyte-to-monocyte ratio (LMR)." (PMID 41574679, 2026).
pancreatic cancer (1 paper, 2023). "LBP could increase tumor-infiltrated lymphocytes, suggesting that LPS has potential as an immunological adjuvant in pancreatic cancer." (PMID 37628784, 2023).
peripheral nerve injury (1 paper, 2013). Injury to a peripheral nerve. "LBP, a mediator of innate immunity, is up-regulated in the PFC of animals with peripheral nerve injury." (PMID 23597049, 2013). "Altered LBP expression in the PFC in response to SNI might be playing similar roles in the gene networks, possibly mediating cortical neuroinflammation in animals with peripheral nerve injury." (PMID 23597049, 2013).
polycystic ovary syndrome (1 paper, 2023). A disorder that manifests as multiple cysts on the ovaries. "In humans, blood serum levels of LPS, LPS to high-density lipoprotein (HDL) ratio, and LPS-binding protein (LBP) were all found to be significantly elevated in polycystic ovary syndrome." (PMID 38260148, 2023).
renal carcinoma (1 paper, 2022). A carcinoma arising from the epithelium of the renal parenchyma or the renal pelvis. "The product of LBP, the lipopolysaccharide binding protein (LBP), is a serum protein that binds and transports LPS (lipopolysaccharide ) It is associated with a worse prognosis in colorectal and renal carcinoma." (PMID 35453754, 2022).
renal fibrosis (1 paper, 2014). A final common manifestation of a wide variety of chronic kidney diseases characterized by glomerulosclerosis and tubulointerstitial fibrosis. "In our model, CPFA treatment could significantly limit renal fibrosis and EC dysfunction by an efficient removal of the LPS-adaptor protein LBP." (PMID 25261195, 2014).
respiratory infections (1 paper, 2015). "Aim of the present study was to evaluate the suitability of Lf, CRP, LBP, and Hp as local biomarkers in respiratory infections in cattle using a well-defined animal model." (PMID 26209015, 2015). "Beside LBP, the suitability of Hp and Lf as local biomarkers of respiratory infections in cattle and their role in the local response to pathogens is worth further investigation, while CRP does not seem to play a role in local defense mechanisms of the bovine lung." (PMID 26209015, 2015).
sensitization (1 paper, 2021). "Our findings suggest that increased LBP level are associated with food allergic sensitization which is in agreement with these studies." (PMID 33495502, 2021). "The major finding of the current study is that the presence and severity of food allergic sensitization is positively associated with serum LBP level." (PMID 33495502, 2021).
Splenomegaly (1 paper, 2022). Abnormal increased size of the spleen. "Tumor resection ameliorated circulating LBP, splenomegaly, and splenic cytokines, but not other parameters associated with loss of colonic barrier integrity and bacterial translocation." (PMID 35248004, 2022).
thrombosis (1 paper, 2015). "We collected samples from patients with and without thrombosis and compared plasma levels of lipopolysaccharide (LPS), LPS binding protein (LBP), soluble CD14 (sCD14), and von Willebrand Factor antigen level (vWF)." (PMID 25814984, 2015).
urinary tract infection (1 paper, 2025). "Plasma LBP levels were similar between patients with pulmonary and urinary tract infections in comparison to patients with other causes of disease in the entire cohort (p = 0.828), in males (p = 0.707) and females (p = 0.266)." (PMID 39997462, 2025).
vitiligo (1 paper, 2023). Generalized well circumscribed patches of leukoderma that are generally distributed over symmetric body locations and is due to autoimmune destruction of melanocytes. "In mice with monobenzone-induced vitiligo, LBP treatment attenuated the symptoms of a vitiligo-like skin disease, inhibited infiltration of CD8+ T cells and reduced activity of the STAT3-Hsp70-CXCL9/CXCL10 signalling pathway." (PMID 36655287, 2023). "In the present study, we observed increased levels of IL-8, IL-6, TNF-α, IFN-γ and IL-1β in the skin of monobenzone-induced vitiligo mice, and LBP significantly inhibited secretion of IL-8, IL-6, TNF-α, IFN-γ and IL-1β." (PMID 36655287, 2023). "The LBP treatment showed down-regulated levels of CD8+ T cells in the skin of mice with monobenzone-induced vitiligo." (PMID 36655287, 2023). "To assess whether LBP influences CD8+ T cells in the skin of mice with monobenzone-induced vitiligo, we measured CD8+ T cells expression using immunofluorescence." (PMID 36655287, 2023). "To assess whether LBP influences innate immune responses in the skin of mice with monobenzone-induced vitiligo, we measured IL-8, IL-6, TNF-α, IFN-γ and IL-1β expression by RT-qPCR." (PMID 36655287, 2023). "Our study showed that LBP can down-regulate the ratio of p-STAT3/STAT3 in skin lesions of monobenzone-treated mice, suggesting that LBP may inhibit the activation of the STAT3-Hsp70-CXCL9/CXCL10 pathway in vitiligo treatment." (PMID 36655287, 2023).
ZIKV infection (1 paper, 2025). "Thus, we assessed plasma levels of LBP before and after ZIKV infection of PTMs." (PMID 40827913, 2025).
infection (101 papers, 2006 to 2026). The state of being infected such as from the introduction of a foreign agent such as serum, vaccine, antigenic substance or organism. "This review aims to summarize the investigation and association of SNPs in the LBP gene with infections and inflammatory diseases, metabolic disorders and cancers." (PMID 34295331, 2021). "To measure microbial translocation, we quantified the concentration of LBP throughout infection in the plasma by enzyme-linked immunosorbent assay (ELISA)." (PMID 30326919, 2018). "Studies demonstrated that LBP deficiency protected mice from LPS stimulation but exhibited higher lethality in bacterial stimulation, which might account for that carriers of rs2232613 exhibited higher risk of severe clinical infection." (PMID 34295331, 2021). "The purposes of this study were to investigate the role of the LBP gene in response to bacterial pathogen infections, and to examine whether SNPs in the gene were associated with the resistance to two major bacterial pathogens of tilapia: S. agalactiae and A. hydrophila." (PMID 25470022, 2014). "In the liver, the expression of ToBPI1/LBP and ToBPI2/LBP peaked at 6 h and 72 h, respectively, following the infection with V. alginolyticus." (PMID 37107584, 2023). "In the S. agalactiae group, ToBPI1/LBP and ToBPI2/LBP peaked in the liver after infection at 12 h and 6 h, respectively." (PMID 37107584, 2023). "After infection with S. agalactiae and V. alginolyticus, the expressions of ToBPI1/LBP and ToBPI2/LBP in the liver, head, kidney and spleen increased considerably." (PMID 37107584, 2023). "Bactericidal/permeability-increasing protein (BPI) and lipopolysaccharide-binding protein (LBP) are a group of antibacterial proteins that play an important role in the host’s innate immune defense against pathogen infection." (PMID 37107584, 2023). "Multiple biomarkers, including IP-10, IL-6, sCD163, leptin, IL-8, and LBP were variable either within each participant’s two pre-infection or two post-ART-suppression specimens." (PMID 37461626, 2023). "During infection it is released from bacterial cells to the blood where it is bound to LPS binding protein (LBP) and through CD14 and TLR4 (Toll-like receptor) induces macrophages to the pro-inflammatory cytokines secretion." (PMID 36339335, 2022). "In the case of infection, LPS is extracted from bacterial membranes and bound to LPS binding protein (LBP), which transfers LPS through interaction with CD14 to toll-like receptor 4 (TLR4)." (PMID 35326484, 2022). "Evidence of gut barrier dysfunction was minimal at the time of vaccination, with only 2 animals displaying elevated plasma levels of lipopolysaccharide binding protein (LBP) compared to pre-infection levels." (PMID 34992610, 2021). "In this review, we aim to present the current knowledge regarding the occurrence of SNP in the LBP gene and the impact of SNP in the LBP gene on the development and the course of selected infections, inflammatory diseases, metabolic disorders and cancers." (PMID 34295331, 2021). "As a key participant in the inflammatory response to infection, LBP is a type I acute phase response protein produced by a variety of cell types, which can enhance the recognition of endotoxins and pathogens by the immune system." (PMID 34199615, 2021). "Given the crucial role of LBP in inflammation, we will review the impact of SNPs in the LBP gene on infections and inflammatory diseases, metabolic disorders and cancers." (PMID 34295331, 2021). "CD14 is the receptor for lipopolysaccharide (LPS) / LPS – binding protein (LPS/LBP) complexes and is released in the early phase of infection." (PMID 32503419, 2020). "Similar to CRP, Saa and LBP are known to be induced during bacterial infections and infection with Candida species and thus these proteins seem unsuitable for differentiating between fungal and bacterial infection." (PMID 33043780, 2020).